CSF1 (colony stimulating factor 1)
Diseases named in the same sentence as CSF1 in open-access papers (continued):
Sharing a sentence is not in itself a finding about the gene and the disease.
tumor (continued). "The treatment of mice co-injected with IBC cells and MSCs with anti-CSF1 inhibited tumor associated macrophages and inhibited pSTAT3 expression in tumor cells." (PMID 27756885, 2016). "Tumor cell-derived CSF-1 has also been linked to the proliferation of a protumor subset of CD11bloF4/80hi macrophages in the MMTV-Neu transgenic model of mammary tumor growth." (PMID 26884646, 2016). "Tumor associated macrophages (TAMs) stimulated by CSF1 have a wide range of activities like promoting tumor growth, angiogenesis, extracellular matrix breakdown." (PMID 27107415, 2016). "They demonstrated that CTC levels and lung metastases were significantly decreased in CSF-1-deficient mice as compared to wild type mice, supporting a role for tumor infiltrating macrophages in metastasis." (PMID 26980947, 2016). "In this study, we analyzed CSF-1 expression by immunohistochemistry in ccRCC tumor tissues and its association with clinicopathologic characteristics and patient outcome." (PMID 25886010, 2015). "CSF1-dependent monocytes and monocyte-derived cells including tumor-associated macrophages, MDSCs, and moDCs express a vast range of receptors to sense the local environment and are highly plastic in their response to various stimuli." (PMID 26635798, 2015). "There was also observed maspin association with chromatin at the promoter of colony-stimulating factor-1 (CSF-1), which caused inhibition of tumor growth." (PMID 24581141, 2014). "For instance, the pancreatic islet cancer model of CSF-1-deficient op/op mice displayed a substantial reduction in macrophage infiltration, angiogenic switching, and cumulative tumor burden." (PMID 25125485, 2014). "Depletion or inhibition of CSF-1 suppresses the infiltration of TAMs, which is associated with a significantly impaired tumor progression." (PMID 24314323, 2013). "In agreement, knockout mice for the primary tumor macrophage chemoattractant, CSF-1, have a slow tumor growth and reduced metastasis, and CSF-1 levels have been associated with poor prognosis in several human malignancies." (PMID 23762835, 2013). "Using Csf1op/op mice, which are deficient in the macrophage growth factor CSF1, a recent study has demonstrated a crucial role for macrophages in regulating tumor progression." (PMID 24224029, 2013). "Certain cytokines (e.g., IL-6 and CSF-1) can influence the phenotype and the function of tumor-associated macrophages and indirectly stimulate tumor invasiveness and angiogenesis." (PMID 23024650, 2012). "According to previous studies, the overexpression of the fusion protein, Runx1-Runx1t1 causes the downregulation of Csf-1 (a hematopoietic cytokine known to cause activation of microglia) and Runx3 (a tumour suppressor)." (PMID 22697290, 2012). "This proliferation was induced either by ectopic CSF-1, that mimic CSF-1 produced by fibroblasts and monocytes/macrophages associated with the tumor, or autocrine CSF-1." (PMID 22096574, 2011). "Co‐culture of MDA‐MB‐231 breast cancer cells with monocytes and endothelial cells in the presence of interstitial fluid flow significantly enhances the activation of monocytes to tumor‐associated macrophages (TAM)‐like phenotype through stimulation by colony‐stimulating factor 1 (CSF‐1)." (PMID 40150879, 2025). "CSF-1/CSF-1R signaling is important for tissue homeostasis, repair, and inflammation and acts as a chemoattractant for the recruitment, production, and survival of tumor-associated macrophages (TAMs) in the tumor microenvironment." (PMID 40646332, 2025). "Huang Y.H., Cai K., Xu P.P., Wang L., Huang C.X., Fang Y., Cheng S.,Sun X.J., Liu F., Huang J.Y., Ji M.M., Zhao W.L. CREBBP/EP300mutations promoted tumor progression in diffuse large B-cell lymphomathrough altering tumor-associated macrophage polarizationvia FBXW7-NOTCH-CCL2/CSF1 axis." (PMID 41541561, 2025).
tumor (continued). "Furthermore, ZMYND8 upregulation augments the secretion of CSF1, a pivotal chemokine instrumental in recruiting and polarizing tumor-associated macrophages (TAMs) toward an M2-like, immunosuppressive phenotype that supports metastatic progression." (PMID 41297414, 2025). "Additionally, injury-like tumor phenotypes were associated with larger tumor size and CSF1-mediated myeloid cell recruitment by VS-SCs, as demonstrated through deconvolution analysis and scATAC-seq13." (PMID 40629113, 2025). "The CSF‐1–CSF‐1R signaling pathway may deplete tumor‐associated macrophage and myeloid‐derived suppressor cells responsible for the immunosuppressive tumor microenvironment (TME)." (PMID 40717900, 2025). "Moreover, high CSF-1 expression at the tumor periphery has been associated with an increased risk of metastatic spread." (PMID 41409281, 2025). "The expression of CCL-2 and CSF-1 by reactive astrocytes is particularly significant, as it appears to regulate the recruitment of tumor-associated macrophages and their subsequent reprogramming into a phenotype that supports HGG growth and invasion (Perelroizen and others 2022)." (PMID 39066464, 2025). "CSF1 is a vital cytokine involved in the regulation of monocyte/macrophage differentiation, proliferation, and survival, and its signaling is necessary for the accumulation of tumor-associated macrophages." (PMID 39044819, 2024). "To investigate whether the upregulation of CSF-1 in EBV-associated tumour cells regulates CCR5 receptor expression on monocytes and migration towards rh-CCL5, we performed chemotaxis experiments in an rh-CCL5 and CSF1 receptor (CSF1R)-inhibited system." (PMID 39267775, 2024). "Notably, tumor-associated macrophage membrane-functionalized nanoparticles suppress CSF1 and interactions between cancer cells and the tumor microenvironment, impairing tumorigenesis." (PMID 38566199, 2024). "High levels of CSF-1 expression in TNBC are associated with higher tumor grades." (PMID 39409110, 2024). "Indeed, CSF-1 response signatures are found in 25% of breast cancers, which marks the activation of reprogrammed TRMs and is associated with high tumor proliferation and higher grades." (PMID 39104525, 2024). "Tumor microenvironment genes linked to ocular angiogenesis include Spp1, Csf1, and Cxcr4." (PMID 37858232, 2023). "Eliminating tumor-derived CSF1 results in decreased tumor growth and enhanced immunity against tumor-associated neoepitopes, potentially promoting an immune permissive tumor microenvironment in tumor-bearing mice." (PMID 37505292, 2023). "Although iCAFs downregulated TGFB3 during treatment compared to pre-treatment, they may still promote monocyte survival and differentiation into tumor-associated macrophages by overexpressing macrophage colony-stimulating factor-1 (CSF-1)." (PMID 37833788, 2023). "In addition to its essential physiological role in normal tissues, the CSF1/CSF1 receptor axis is known to be overexpressed in many tumor types and associated with poor prognosis." (PMID 37505292, 2023). "Moreover, CSF1 promotes the differentiation of monocytes into tumor-associated macrophages (TAMs), which in turn facilitates tumor survival, growth, and metastases with their immunosuppressive effects." (PMID 36209184, 2022). "The high expression of CSF1R on multiple cell types and the associated increase in Ki67+ tumor cells suggested to us that targeting the CSF1/CSF1R axis might enhance palbociclib efficacy by countering CSF1R-mediated processes." (PMID 35788566, 2022). "CSF-1 is associated with tumor progression, metastasis, angiogenesis, and treatment resistance." (PMID 36419877, 2022). "In addition to cell-cell contact, tumor cells can release plenty of molecules with associated receptors on macrophages, such as CSF-1, Chemokines, and IL-10, resulting in the reprogramming of macrophages." (PMID 36497444, 2022).
tumor (continued). "Along this line, our data demonstrates that high HCC UHRF1 causes increased tumor CSF1 production by reducing DNMT1-mediated DNA methylation in the CSF1 promoter; subsequently, tumor CSF1 promotes TAM tumor infiltration and boosts TAM COX-2 expression and PGE2 production." (PMID 35664070, 2022). "CSF-1-activated tumor-associated macrophages can contribute to tumor growth and metastasis." (PMID 36624801, 2022). "Besides, tumor-associated macrophage accelerates the survival of CRPC cells upon docetaxel chemotherapy via the CSF1/CSF1R-CXCL12/CXCR4 axis." (PMID 36686485, 2022). "Lactic acid accumulation within the TME may alter the functions and antigen phenotype of these DCs, and lactic acid alone or in combination with IL-6 and macrophage colony-stimulating factor 1 (M-CSF) may result in a tumor-associated DC phenotype." (PMID 36276846, 2022). "Indeed, the depletion of tumor-associated macrophages via inhibiting either CSF1/CSF1R or CCL2/CCR2, are both capable of overcoming T cell exclusion within tumors." (PMID 33927723, 2021). "In B-lymphoma cells, the mutation or knockdown of CREBBP or EP300 inhibited H3K27 acetylation, downregulated FBXW7 expression, activated the NOTCH pathway, and downstream CCL2/CSF1 expression, resulting in tumor-associated macrophage polarization to M2 phenotype and tumor cell proliferation." (PMID 33431788, 2021). "Both FGF and CSF-1 signaling are involved in immune evasion through the recruitment and maintenance of myeloid-derived suppressor cells and tumor-associated macrophages to the tumor microenvironment." (PMID 33916707, 2021). "In addition, the expression of CSF1 in the tumor microenvironment is associated with the recruitment, accumulation and polarization of tumor-associated macrophages." (PMID 34298983, 2021). "It was reported that CSF1/CSF1R blockade-based anti-tumor therapy could result in loss of macrophages in the tumor either by mitigating recruitment, TAMs survival and/or differentiation from monocytes." (PMID 34248982, 2021). "CSF1 is another kind of cytokine, which is located on chromosome 1p13.3, could promote the infiltration and survival of tumor associated macrophages (TAMs)." (PMID 34335194, 2021). "CSF1 is a factor that can promote the formation of tumor-associated macrophages." (PMID 34900411, 2021). "CSF1 has been implicated in the recruitment and polarization of M2, which once activated can release trophic cytokines and pro-angiogenic factors to enhance tumor cell growth." (PMID 33466385, 2021). "CSF1/CSF1R signaling mediates tumor-associated macrophages recruitment and M2 polarization." (PMID 34067348, 2021). "CSF1 is a macrophage marker which splice variant could correlate with infiltration of tumour-promoting macrophages." (PMID 33845831, 2021). "Colony stimulating factor-1 (CSF-1), a polypeptide chain cytokine, and its receptor CSF-1R are reported to play important roles in regulating tumor-associated macrophages in tumor microenvironment and participating in the occurrence and development in diversities of cancers." (PMID 34729112, 2021). "Therefore, it is important to explore the CSF-1 and CSF-1R signaling pathways related to tumor-associated macrophages (TAM) and their specific mechanisms in the comprehensive prevention and treatment of gastrointestinal malignancies." (PMID 34729112, 2021). "This signalling also promotes BCCs to secret CSF1, which will bind to the CSF1 receptor on MSCs, tumor-associated macrophages and myeloid-derived suppressor cells, and drive recruitment of myeloid-derived suppressor cells (MDSCs) and tumor-associated macrophage (TAMs)." (PMID 33849537, 2021). "Importantly, a strong correlation of CSF-1 expression with CSF-1R-positive tumor-associated macrophage infiltration has also been detected in human carcinomas." (PMID 32637413, 2020).
tumor (continued). "Tumor cells are able to switch the potential phenotype of macrophages into tumor-associated macrophages, which are characterized as the M2d subtype, through the production of colony stimulating factor 1 (CSF1) for example." (PMID 35582435, 2020). "Interestingly, SFKs are crucial mediators of the CSF-1-CSF-1R-induced maturation of migratory tumor-associated macrophages." (PMID 32664483, 2020). "The EOC cells, for instance, are able to polarize macrophages toward a tumor-associated phenotype by secreting several factors, such as the colony-stimulating factor 1 (CSF-1), which acts as both a chemoattractant and a mitogen for circulating monocytes via tyrosine kinase receptor CSF1-R binding." (PMID 31096567, 2019). "Moreover, CSF-1 and CSF-1R are also expressed in tumor-associated macrophages (TAMs), promoting tumor progression and metastasis in several cancers." (PMID 31565097, 2019). "In addition, growth factors, such as CSF1, stimulate tumor associated macrophages to be anti-inflammatory, or the M2 phenotype, and promote tumor growth." (PMID 30841880, 2019). "In the tumor microenvironment, macrophages are infiltrated (they are called ‘tumor-associated macrophages’) and activated, expressing CSF-1 and CCL2, which may promote intravasation and metastasis." (PMID 30496442, 2019). "CSF-1/CSF-1R axis has been recently proposed to associate with a hybrid E/M phenotype in inflammatory breast cancer —a highly aggressive breast cancer subtype that metastasizes via clusters or emboli of circulating tumor cells." (PMID 31121840, 2019). "CSF-1 is associated with macrophage programs that promote tumor growth, and tumor cell secretion of CSF-1 may be an adaptive feature of some cancers." (PMID 29757143, 2018). "Consistent with the role of CSF-1-dependent, TAM-activated tumor invasion, high CSF-1 levels are also associated with poor prognoses in many cancers, leading to the testing of a variety of anti-CSF-1/CSF-1R therapies to either reduce or reprogram TAMs to treat cancer." (PMID 28629162, 2017). "However CSF-1 deficient mice had lower macrophage number and decreases in tumour progression and metastatic spread." (PMID 27212807, 2016). "Finally, immunohistochemical analysis of primary human lung tumors revealed a positive correlation between Vav1 and CSF1 expression, which was associated with tumor grade." (PMID 25313137, 2014). "We then wondered what are the possible additional sources for CSF1 in the tumor microenvironment and hypothesized that tumor associated macrophages (TAMs) are a likely candidate." (PMID 25313137, 2014). "While increased CSF1 levels can be associated with malignancy and metastasis, tumor progression and development may also be dependent on whether CSF1 is derived from tumor cells, stromal cells or both." (PMID 25313137, 2014). "However, restoring CSF-1 showed that tumor-associated macrophages play a key role in fostering tumor angiogenesis which is an essential step in the tumor progression to malignancy." (PMID 23673510, 2013). "Depletion of macrophages in this tumor model using mice carrying the homozygous null allele (Csf1op) for the monocyte growth factor, colony stimulating factor (CSF)-1, caused a 50% reduction in vascular density and resulted in delayed tumor progression and metastasis." (PMID 23847541, 2013). "Nuclear localization of SERPINB5 is required for its tumor metastasis suppressor function and it was enriched at the promoter of colony-stimulating factor (CSF-1) in chromatin immunoprecipitation and associated with diminished levels of CSF-1 mRNA." (PMID 23217164, 2012). "In addition, the presence of tumor associated macrophages in breast tumors also correlates with poor prognosis and, in mouse models, CSF-1 promotes metastasis, stimulates angiogenesis and is involved in a paracrine loop with EGF to promote tumor cell invasion." (PMID 22096574, 2011).
tumor (continued). "Moreover, tumor cells recruit macrophages called tumor associated macrophages (TAMs) by secreting the colony stimulating factor (CSF-1), the chemokine ligand 2, 3, 4, 5, and 8 (CCL2, 3, 4, 5, and 8) and the vascular endothelial growth factor (VEGF)." (PMID 21437225, 2010). "The data with this cell line confirmed that observed with primary tumor isolates and indicated that the metastatic potential of Met-1 cells was reduced with both seeding and persistent growth being significantly affected according to the host CSF-1 deficiency." (PMID 19668347, 2009). "They found that the CSF-1/CSF-1R signaling pathway induced hematopoietic progenitor cells and stem cells derived from bone marrow within the tumor differentiating into M2 tumor-associated macrophages, which contributed to tumor survival and regeneration after radiotherapy." (PMID 40007537, 2025). "In addition, in poorly differentiated high-grade PDAC, particularly with a mesenchymal subtype, elevated secretion of colony-stimulating factor 1 (CSF-1) promotes the differentiation of monocytes into anti-inflammatory M2-like tumor-associated macrophages (TAMs)." (PMID 39859231, 2025). "Moreover, the metastatic activity of CSF-1 was mediated by the downstream activation of the urokinase-type plasminogen activator (uPA) pathway, which was linked to motility and invasiveness in several tumor types." (PMID 38254773, 2024). "Therefore, blocking the CSF-1/CSF-1R axis could be effective for inhibiting the association between TAMs and tumor cells." (PMID 39169402, 2024). "While this phenotype might be associated with tumor immune escape, we hypothesized that the change from CSF1 to IL-34 could be important during the MFAP5 + fibroblasts mediated promotion of tumor malignancy through the driving of the immune evasive phenotype of C1QC + macrophages." (PMID 37344903, 2023). "The strong negative prognostic value of the macrophage colony-stimulating factor CSF1/M-CSF in iCCA, with higher expression shown specifically in iCCA tumor-infiltrating T-cells, furthermore, implicates tumor associated macrophages as important actors in the promotion of tumor progression." (PMID 37404757, 2023). "CSF1 promotes tumor-associated macrophages (TAMs) that may undermine anti-tumor immune responses." (PMID 35247086, 2022). "Previous research has indicated PTPN11 could bind to the colony-stimulating factor receptor (CSF-1R) complex in response to CSF-1 stimulation in the tumor-associated macrophages to stimulate the Ras/Erk pathway, which can enhance tumor cell proliferation and migration." (PMID 35802774, 2022). "Recruited by macrophage chemo-attractants (i.e, CCL2, MCP1, CSF-1), tumor-associated macrophages represent up to 50% of tumor-infiltrating cells, as seen in melanoma, renal cancer, and colonic carcinoma, suggesting they may be able to efficiently infiltrate into solid tumors upon adoptive transfer." (PMID 33790906, 2021). "In addition, loss of the chromosome 17p arm was identified in both tumour and CSF1." (PMID 33110059, 2020). "In addition to the SDF-1/CXCR4 pathway enhanced by radiation-induced tumor hypoxia, the CSF-1/CSF1R signaling complex has also been recently implicated in recruitment of myeloid cells to growing tumors and in promoting the radiation-induced monocytic infiltration of tumors." (PMID 23882218, 2013). "For example, tumor cell-secreted CSF-1 promotes the influx of monocyte precursors expressing the CSF-1 receptor (CSF-1R) and promotes their differentiation into M2 TAMs." (PMID 41590379, 2026). "Mechanistically, high OPN expression activates the PI3K/AKT signaling pathway in macrophages, promoting the secretion of CSF1, which induces M2-like polarization of macrophages to facilitate tumor metastasis." (PMID 41639044, 2026). "Due to the central involvement of CSF-1/CSF-1R signaling in the attraction of TAMs to tumor sites and endorsement of M2 differentiation, CSF-1/CSF-1R targeting has become an appealing therapeutic strategy." (PMID 41590379, 2026).